KLRC3 (killer cell lectin like receptor C3)
Description:
Plays a role as a receptor for the recognition of MHC class I HLA-E molecules by NK cells and some cytotoxic T-cells.
Synonyms: NKG2E; NKG2-E
Tractability: Antibody: UniProt predicts a signal peptide or a membrane-spanning region; its Gene Ontology location is reachable by antibodies, with medium confidence.
Gene: Protein-coding gene on chromosome 12 (10,412,315 to 10,420,595, reverse strand). Ensembl gene ENSG00000205810.
Subcellular location: Membrane
Subcellular location (Human Protein Atlas): Vesicles
Gene Ontology:
Molecular function: activating MHC class Ib receptor activity; transmembrane signaling receptor activity
Biological process: cellular defense response; natural killer cell mediated immunity; positive regulation of natural killer cell mediated cytotoxicity; regulation of natural killer cell activation; stimulatory C-type lectin receptor signaling pathway
Cellular component: cell surface; plasma membrane; membrane
Genetic constraint (gnomAD): Loss-of-function variants: 13 observed, 16.51 expected, observed/expected ratio (o/e) 0.79, 90% interval 0.51 to 1.25. The upper end of that interval is the gene's LOEUF score, 1.25, which puts it in group 5 of 6, group 1 being the genes least tolerant of losing a copy. Missense variants: 148 observed, 180.05 expected, observed/expected ratio (o/e) 0.82, 90% interval 0.72 to 0.94. Synonymous variants: 57 observed, 55.1 expected, observed/expected ratio (o/e) 1.03, 90% interval 0.83 to 1.29.
Homologues: Orthologues: chimpanzee KLRC3 (89% identical), mouse Klre1 (20% identical), rat Klri1 (20% identical), mouse Klri1 (20% identical), rat Klre1 (19% identical), rat Klrh1 (18% identical), zebrafish si:ch211-170d8.8 (18% identical), Drosophila melanogaster rgn (17% identical), rat Klri2 (17% identical), mouse Klri2 (17% identical), zebrafish si:dkey-26c10.5 (16% identical), Caenorhabditis elegans clec-146 (16% identical), and 5 more. Paralogues in human: KLRC2 (86% identical), KLRC1 (67% identical), KLRC4 (52% identical), CLEC12B (20% identical), KLRD1 (20% identical), CLEC12A (20% identical), CLEC7A (19% identical), KLRB1 (19% identical), KLRG1 (18% identical), KLRF1 (17% identical), KLRK1 (17% identical), CLEC1A (17% identical), and 11 more.
Diseases named in the same sentence as KLRC3 in open-access papers:
KLRC3 is named in the same sentence as 24 diseases in open-access papers, as found by Europe PMC text mining. Sharing a sentence is not in itself a finding about the gene and the disease. The quoted sentences say what the papers report.
glioblastoma (5 papers, 2017 to 2023). The most malignant astrocytic tumor (WHO grade IV). "For the first time we report that KLRC3 gene expression is linked to glioblastoma aggressiveness and could be a new potential therapeutic target to attenuate glioblastoma." (PMID 27641066, 2017). "Moreover, in a cohort of 154 patients with glioblastoma, KLRC3 has been founded mutated in 6% of the cases." (PMID 27641066, 2017). "KLRC3 is a natural killer cell receptor gene, and previous studies have shown that KLRC3 affects the stemness and proliferative potential of glioma cells and is involved in glioblastoma tumorigenesis and progression." (PMID 35432443, 2022). "KLRC3, which is identified as a natural killer receptor gene, performs an instrumental function in tumorigenesis and aggressiveness of glioblastoma." (PMID 36059811, 2022). "Radiation did not significantly modify proliferation of shPRUNE2 cells while shKLRC3 cell proliferation was decreased, suggesting KLRC3 involvement in glioblastoma cells radioresistance mechanism." (PMID 27641066, 2017). "To further understand the mechanism involving KLRC3 in glioblastoma tumourigenesis, we focused on DAP12 protein which has been shown to form a heterodimeric complex with KLRC3 and analysed its expression directly in patients’ samples." (PMID 27641066, 2017). "Accordingly, KLRC3 silencing induces a significant decrease in glioblastoma cells self‐renewal ability suggesting that KLRC3 is of prime importance in the maintenance of CSC subpopulation." (PMID 27641066, 2017). "Among the signalling proteins analysed, we choose to focus on the ones involved in cell radioresistance since we demonstrated that KLRC3 is involved in this glioblastoma phenotype." (PMID 27641066, 2017). "Taken together these findings suggest that KLRC3 plays a major role in glioblastoma aggressiveness." (PMID 27641066, 2017). "Indeed, KLRC3 silencing decreased self‐renewal capacity, invasion, proliferation, radioresistance and tumourigenicity of U87‐MG glioblastoma cell line." (PMID 27641066, 2017). "In this context, we suggested that KLRC3 could be involved in glioblastoma cells radioresistance." (PMID 27641066, 2017). "The putative role of KLRC3 is still unknown in glioblastoma aggressiveness." (PMID 27641066, 2017). "To determine the putative role of CHI3L1, KLRC3 and PRUNE2 genes in glioblastoma aggressiveness, we have assessed the three shRNA cell lines tumourigenic potential." (PMID 27641066, 2017). "Three genes named CHI3L1,KLRC3 and PRUNE2 were found overexpressed in glioblastoma undifferentiated cells (related to CSC) compared to the differentiated ones." (PMID 27641066, 2017). "The comparison of their roles suggest that KLRC3 gene coding for NKG2E, a protein initially identified in NK cells, is more important than both two other genes in glioblastomas aggressiveness." (PMID 27641066, 2017). "To analyse the role of KLRC3, CHI3L1 and PRUNE2 genes in the migration ability of glioblastoma cells we used a matrigel invasion chamber system." (PMID 27641066, 2017). "In the present study, the effect of KLRC3 extinction is compared to those of the two other genes CHI3L1 and PRUNE2 in a human glioblastoma cell line." (PMID 27641066, 2017). "Although silencing of CHI3L1, KLRC3 and PRUNE2 decrease cell proliferation, migration, clonogenicity and tumourigenesis, our results demonstrate that KLRC3 is of prime importance for glioblastoma cells aggressiveness and their ability to promote cancer progression." (PMID 27641066, 2017). "The function of KLRC3 is not restricted to its effect on radiosensitivity but also concern glioblastoma self‐renewal property which is significantly decreased compared to CHI3L1 extinction." (PMID 27641066, 2017). "Based on our previous study describing an overexpression of three glycosylation‐related genes, KLRC3, CHI3L1 and PRUNE2 in glioblastomas undifferentiated cells related to CSC, we assessed whether these genes are closely linked to glioma tumourigenesis mechanisms." (PMID 27641066, 2017).
glioblastoma (continued). "The decrease in DAP12 expression level in shKLRC3 cells associated with the significant decrease in the GSK3β protein strongly supports the hypothesis of a link between KLRC3 and DAP12 in the regulation of the glioblastoma aggressiveness, particularly in the radioresistance phenotype." (PMID 27641066, 2017).
endometrial cancer (3 papers, 2019 to 2024). Primary or metastatic malignant neoplasm involving the endometrium (mucous membrane that lines the endometrial cavity). "Only recently a study provided a potential molecular mechanism for ADSL in endometrial cancer oncogenesis, by increasing killer cell lectin-like receptor C3 expression through fumarate production." (PMID 31729379, 2019). "Moreover, fumarate accumulation is linked with endometrial cancer aggressiveness, via adenylosuccinate lyase (ADSL) and killer cell lectin-like receptor C3 (KLRC3): the knock-down of ADSL decreases KLRC3 that in turn reduces cell proliferation, migration and invasion." (PMID 34065551, 2021).
glioma (3 papers, 2017 to 2022). A benign or malignant brain and spinal cord tumor that arises from glial cells (astrocytes, oligodendrocytes, ependymal cells). "In contrast, KLRC3 silencing decreases cell proliferation significantly and even more significantly after cell radiation, suggesting its involvement in glioma radiosensitivity." (PMID 27641066, 2017). "Since KLRC3 has never been linked to glioma, its mechanism of action in this model remains unknown." (PMID 27641066, 2017).
asthma (2 papers, 2012 to 2019). "The up-regulated genes have been previously associated with asthma; hyper-reactivity and allergy (CCR2, HRH2, PTEN); lung development and apoptosis (CHRNA7, RTKN2); and immune function (GIMAP4, GIMAP7, KLRC3 and CD99)." (PMID 30971730, 2019).
malaria (2 papers, 2013 to 2020). Malaria is a serious and sometimes fatal disease caused by a parasite that commonly infects a certain type of mosquito which feeds on humans. "Klrd1, Klrc1, and Klrc3 reveal similar expression courses in response to malaria and to vaccination." (PMID 33202767, 2020). "Gene expression levels were greater than two-fold change in acute febrile malaria including: Fc alpha receptor, Fc gamma receptor 3B, Fc epsilon receptor 1G, PI3K, MAP2K2, Arf6, KLRC3, KIR3DL2, and CEBP gamma (range two- to four-fold)." (PMID 24188121, 2013).
Sepsis (2 papers, 2021 to 2024). Sepsis is defined as life-threatening organ dysfunction caused by a dysregulated host response to infection. "Although we observed increased NK frequencies in CCI, we have previously demonstrated via scRNA-seq analysis that cytotoxic genes (KLRC3, KLRC1, and KLRG1) of NK cells were downregulated in patients with late sepsis (CCI and rapid recovery) (n=4), suggesting dysregulation of these cells." (PMID 39691721, 2024).
autoimmune disease (1 paper, 2023). A disorder resulting from loss of function or tissue destruction of an organ or multiple organs, arising from humoral or cellular immune responses of the individual to their own tissue constituents. "Although the role of KLRC3 in APS and RIF pathogenesis has not yet been investigated, it is associated with the development of other autoimmune diseases, metabolic diseases, and tumors." (PMID 37901230, 2023).
COVID-19 (1 paper, 2022). A disease caused by infection with severe acute respiratory syndrome coronavirus 2. "Comparison between the disease conditions indicated significantly stronger expression of certain NK cell receptors (CD160, KLRC2, KLRC3, KLRF1, KIR3DL2, NCR1, NCR3) along the SLEC lineage in mild COVID-19 compared to severe COVID-19." (PMID 36591270, 2022).
influenza (1 paper, 2018). An acute viral infection of the respiratory tract, occurring in isolated cases, in epidemics, or in pandemics; it is caused by serologically different strains of viruses (influenzaviruses) designated A, B, and C, has a 3-day incubation period, and usually lasts for 3 to 10 days. "However, it is also possible that KLRC3 expression in the blood simply reflects the number of NK cells present and that KLRD1-expressing NK cells are protective against influenza using a mechanism independent of NKG2E or NKG2H signaling." (PMID 29898768, 2018).
lung adenocarcinoma (1 paper, 2022). A carcinoma that arises from the lung and is characterized by the presence of malignant glandular epithelial cells. "KLRC3 may be a core gene suitable for prognosis in lung adenocarcinoma and is associated with SD/PD and CR/PR patients, which will improve reference for future immunotherapy-related studies." (PMID 35432443, 2022).
tumor (10 papers, 2017 to 2025). "Their findings indicated that ADSL enhances tumor cell proliferation, invasion, and migration by modulating KLRC3 expression." (PMID 38433141, 2024). "Accordingly, in GBM, a tumor where oncometabolites are often increased, the fumarate-dependent increase of KLRC3 has been correlated with radio-resistance and poor outcome." (PMID 34065551, 2021). "Apart from SAR1B, ZBTB33, STYX, KLRC3, and S100Z, there were significant differences in the other 10 DEGs levels in the tumor-stroma crosstalk." (PMID 30519576, 2018). "We used a primary culture derived from a patient tumour and show that both KLRC3 and DAP12 proteins are expressed in the primary culture." (PMID 27641066, 2017). "Furthermore, the tumour volumes for shKLRC3 as well for shCHI3L1 grafts (50 mm3) were significantly reduced compared to shPRUNE2 grafts (150 mm3) suggesting that KLRC3 and CHI3L1 might be of prime importance in tumourigenesis process." (PMID 27641066, 2017). "Interestingly, the shKLRC3 cells have formed tumour mass in only 30% of the engraftment meaning that the extinction of the KLRC3 gene could reduce the tumourigenicity of the U87‐MG cells." (PMID 27641066, 2017). "Fumarate recovers KLRC3 expression in ADSL-knocked down cells, counteracting these anti-tumor effects and contributing to cancer aggressiveness." (PMID 34065551, 2021). "In this work we observed an overexpression of three specific glycosylation‐related genes, CHI3L1, KLRC3 and PRUNE2 in CSC from cancer cell lines and human primary tumour cells." (PMID 27641066, 2017). "Notably, the anti-tumor activities of natural killer (NK) cell family receptors, including KLRC1 and KLRC3, have been reported in different cancers and cancer phases, particularly in metastasis." (PMID 39227808, 2024). "Notably, mRNAs regulated by miR-141 were highly enriched for transcripts subject to cancer repression, and the miR-141-dependent regulation of many curtail tumor suppressor mRNAs, including the KLRC1, KLRC3, CAM3, CAM5, CAM6, and CAM7 was approved." (PMID 39227808, 2024). "Cluster3 of both subsets (which we refer to as NK-innate-likeCD28− and CD28+, respectively), represented in peripheral blood and reduced at the tumor site, were characterized by the expression of NK-like markers KLRB1, KLRC3, and KIR2DL1, along with IKZF2 and ZBTB16 (PLZF)." (PMID 37898752, 2023). "In contrast to TCGA LGG dataset, high tumor expression of KLRC1 and KLRC2 in CGGA LGG patients were associated with improved prognosis, but not KLRC3, KLRC4 or KLRK1." (PMID 34539622, 2021).
cancer (4 papers, 2017 to 2025). A tumor composed of atypical neoplastic, often pleomorphic cells that invade other tissues. "Fumarate affects the migration and invasion of cancer cells by acting on the killer cell lectin-like receptor C3." (PMID 34357350, 2021). "Unlike PRUNE2 and CHI3L1 proteins, KLRC3 gene coding for NKG2E protein, has never been reported in cancer." (PMID 27641066, 2017).
infection (3 papers, 2018 to 2022). The state of being infected such as from the introduction of a foreign agent such as serum, vaccine, antigenic substance or organism. "Comparisons across the early- and late-stages of infection showed that cells from CHs had an early expression of genes associated with exhaustion (PDCD1, ENTPD1), and cytotoxicity, including NK-like genes NKG7, GNLY, KLRC2, and KLRC3 (encoding for NKG2C and NKG2E, respectively)." (PMID 36477661, 2022). "Increased expression of KLRD1 and KLRC3 in nasal epithelium samples and reduced frequency of NK cells in peripheral blood samples are consistent with our hypothesis that the NK cells are actively recruited to the site of infection." (PMID 29898768, 2018).
KLRC3 also shares sentences with these, for which no sentence is quoted: breast carcinoma (2 papers); viral infection (2); Allergy (1); antiphospholipid syndrome (1); cervical cancer (1); lymphoma (1); metabolic disease (1); neuroblastoma (1); osteoporosis (1); osteosarcoma (1); psoriasis (1).